STAT3 (signal transducer and activator of transcription 3)
Diseases named in the same sentence as STAT3 in open-access papers (continued):
Sharing a sentence is not in itself a finding about the gene and the disease.
cervical carcinoma (continued). "Notably, we recently demonstrated that, in cervical cancer cells, STAT1 controls PARP1 levels through multiple mechanisms, possibly involving also STAT3." (PMID 37190289, 2023). "Here, we demonstrated a critical role for IFN-γ/STAT1/STAT3 signaling in regulating PARP1 levels in HGSOC cells, in line with our recent results in cervical cancer, and with the emerging evidence on the functional interplay between the STATs signaling cascade and PARP1." (PMID 37190289, 2023). "Additionally, miR-21 was directly correlated with the STAT3/ pSTAT3 expression levels, while let-7a demonstrated a reverse correlation in HPV-infected cervical cancer lesions." (PMID 35164678, 2022). "However, STAT3 and STAT5 probably have the most critical roles in the development of cervical cancer." (PMID 35163748, 2022). "Later, the same researchers measured the levels of miR-21 and let-7a, and investigated their possible correlation with STAT3 in cervical cancer tissues with various grades retrieved from premalignant and malignant lesions in HPV-infected cervical cancer patients." (PMID 35164678, 2022). "(2020) demonstrated that targeting CD109 by siRNA or CRISPR/Cas9 could inhibit cervical cancers’ tumorigenic and aggressive properties by inactivating the CD109/EGFR/STAT3 axis in vitro and in vivo." (PMID 35508982, 2022). "This study found that STAT3 is highly expressed in cervical cancer tissues, has a negative correlation with LC3B, one of the most essential autophagy molecular, and the results of this study are consistent with the results shown in GEO database." (PMID 35057825, 2022). "At the same time, the expression of STAT3 or LC3B in patients with different histological type, differentiation degree, FIGO stage, tumor size, lymph node metastasis and vascular infiltration of cervical cancer was detected by immunohistochemistry." (PMID 35057825, 2022). "In addition, very interestingly, one study found that autocrine and paracrine phosphorylation of STAT3 in HPV-positive cervical cancer cells are driven by activation of the IL-6 signaling axis, thus promoting the proliferation of cervical cancer cells." (PMID 35570248, 2022). "In cervical cancer, miR-146b-3p negatively regulated 15-PGDH involving STAT3 and AKT signaling." (PMID 34194517, 2021). "In addition, the results show that STAT3 and ERK signals, which are sub-signals of p-GP130, were inhibited in SiHa, HeLa, and CaSki cervical cancer cells according to the concentration of Bazedoxifene." (PMID 34445405, 2021). "Importantly, we have shown that STAT3 activity, as well as that of the upstream kinase JAK2, is essential for proliferation and survival of cervical cancer cells." (PMID 33427604, 2021). "The protein levels of p‐STAT3 (Tyr705), N‐cadherin, E‐cadherin, vimentin, MMP‐13, and MMP‐3 in the tumor tissues grown from HeLa cells were determined through IHC and Western blot to examine the effects of RES on STAT3 phosphorylation, EMT, and cervical cancer cell invasion." (PMID 33040485, 2020). "To investigate whether CD109 facilitates the EGFR/STAT3 signalling, we performed a Western blot analysis to determine the expression of CD109 and EGFR, and the phosphorylation of STAT3 in different cervical cancer cell lines." (PMID 32507856, 2020). "Additionally, STAT3 phosphorylation is higher in HPV+ cervical cancers when compared with HPV-negative (HPV-) cervical cancers, suggesting that HPV actively increases STAT3 activity in these cancers." (PMID 32899142, 2020). "Furthermore, we showed that STAT3 depletion or inhibition resulted in a proliferation defect and the induction of apoptosis in HPV+ cervical cancer cells." (PMID 31817106, 2019). "In particular, this study revealed that activation of an IL-6 signaling axis drives the autocrine and paracrine phosphorylation of STAT3 within HPV-positive cervical cancers cells, and that activation of this pathway is essential for cervical cancer cell proliferation and survival." (PMID 31470515, 2019).
cervical carcinoma (continued). "Here, we show that HPV positive cervical cancer cells have higher levels of phosphorylated STAT3 protein when compared with those that are HPV negative." (PMID 31226168, 2019). "The overall abundance of STAT3 protein was also increased in the HPV positive compared with HPV negative cervical cancer cells and this correlated with an increase in the levels of STAT3 mRNA expression in HPV positive compared to the HPV negative cell lines." (PMID 31226168, 2019). "To determine whether the regulation of P-STAT3 protein by MEG3 affects the proliferation and apoptosis of cervical cancer cells, we reversed the regulation of P-STAT3 protein by MEG3 using a STAT3 protein phosphorylation inhibitor niclosamide." (PMID 31320837, 2019). "Antibody-mediated blockade of IL-6 signalling in HPV positive cells inhibits STAT3 phosphorylation, whereas both recombinant IL-6 and conditioned media from HPV positive cells leads to increased STAT3 phosphorylation within HPV negative cervical cancer cells." (PMID 31226168, 2019). "It was found that phosphorylated STAT3 elevated the levels of the anti-apoptotic genes BCL-2 like 1 (BCL-XL), Survivin, and Myeloid Cell Leukemia Sequence 1 (MCL-1) in endometrial and cervical cancer tissues relative to normal tissue samples, aiding in their progression." (PMID 31620362, 2019). "Furthermore, HPGD negatively regulated activities of STAT3 and AKT that promote cervical cancer cell proliferation." (PMID 30333561, 2018). "Our work delineate the underlying molecular mechanisms of BLCAP-mediated inhibition of STAT3 in cervical cancer, and we hypothesis that BLCAP may act as a new potential therapeutic target for various types of STAT3-activated carcinomas." (PMID 28455960, 2017). "Taken together, our work demonstrated that chemotherapy with cisplatin-mediated expression of miR-29b functions as a tumor suppressor through targeting STAT3 signal pathway mediated suppression on proliferation, invasion, EMT procedure and angiogenesis of cervical cancer." (PMID 28122338, 2017). "In this study, we aimed to explore the role of BMX during the development and progression of cervical cancer, and we are the first to report that BMX can promote cell proliferation and tumor formation in cervical cancer by activating PI3K/AKT and STAT3 signaling pathways." (PMID 28514765, 2017). "In cervical cancer cells, previous study showed that propofol could enhance cisplatin-induced apoptosis via EGFR/JAK2/STAT3 pathway." (PMID 28542400, 2017). "In addition, miR-17-5p and miR-20a alleviate the suppressive function of myeloid-derived suppressor cells by modulating STAT3 expression, and miR-17-5p functions as a tumor suppressor by targeting TP53INP1 in cervical cancer cells." (PMID 27765929, 2016). "Thus, we examined the effect of Cucurbitacin D on STAT3 activation and expression of HPV-6 in cervical cancer cells." (PMID 27824155, 2016). "Due to activation of STAT3 and the over-induction of antiapoptotic genes found on cervical cancer cell lines after PRL stimulation, we decided to inhibit the STAT3 activation using the inhibitor AG490; which resulted in an impaired induction of Bcl-xl, Bcl-2, survivin and Mcl-1." (PMID 26346346, 2015). "STAT3 was significantly activated in cervical cancer lines in comparison with non-tumorigenic keratinocytes HaCaT." (PMID 26346346, 2015). "Second, we assessed STAT3 expression by immunohistochemical staining of tissues including 55 pairs of human cervical carcinomas and their matched adjacent non-tumor cervical tissues." (PMID 26389681, 2015). "A recent publication similarly showed that STAT3 knock down in DCs elicited no improvement in in-vivo therapeutic efficacy of monotherapy vaccination in a TC-1 murine cervical cancer model when used by itself." (PMID 24806510, 2014).
cervical carcinoma (continued). "On the contrary, persistent STAT3 activation also checks its negative regulator PTEN which is responsible for its dephosphorylation by inducing specific regulatory microRNA, miR-21 that is found elevated in cervical cancer cells." (PMID 23874455, 2013). "Understanding mechanism of disease pathogenesis particularly focusing on interaction of HPV genes/oncogenes with STAT3 signaling may help in development of novel approaches for therapeutic interventions against HPV infection and cervical cancer." (PMID 20977777, 2010). "Although our result indicated that the activation of Stat3 contributed to a poor prognosis, the mechanism of constitutive activation of Stat3 has not been clarified well in cervical cancer." (PMID 19638983, 2009). "Human kidney (HEK293) and cervical carcinoma (HeLa) cells were also not Src/Stat3 permissive, despite high levels of Stat3 phospho-Y705." (PMID 17967179, 2007). "The elevation of Stat3 phosphorylation is also detected in cervical cancer with or without regional lymph node metastasis." (PMID 17311011, 2007). "In cervical cancer cells (SiHa HPV16-positive cells), curcumin downregulates miR-21, resulting in increased PTEN expression and decreased activation of the signal transducer and activator of transcription 3 gene (STAT3), which acts as a promoter of oncogenesis." (PMID 39445208, 2024). "In cervical cancers, resveratrol could concurrently inhibit STAT3, Wnt, and Notch signaling activations, leading to the growth arrest and apoptosis of cervical squamous cell carcinoma and adenocarcinoma cells." (PMID 38702698, 2024). "We recently demonstrated that in cervical cancer cells (HPV-positive CaSki and C-4I), a perturbation in the balanced expression/activation of STAT1 and STAT3 might improve the efficacy of DNA-damaging treatments, at least partially, by lowering PARP1 levels in tumors." (PMID 37190289, 2023). "However, the relationship between STAT3 and autophagy as an important pathway in regulating the physiology and pathology of cervical cancer cells has not been elucidated." (PMID 35057825, 2022). "Also, CD109, as a result of its role in transforming growth factor-β1 (TGF-β1) signaling and signal transducer and activator of transcription 3 (STAT3) activation, could be an innovative target for cervical cancer therapy." (PMID 35508982, 2022). "In line with our previous results, STAT3 activation was weak or absent in cervical cancer cells." (PMID 34469022, 2021). "However, there are no studies on the effect of STAT3 inhibition in NK cells and its response against cervical cancer cells." (PMID 34831327, 2021). "IL‐6 was used to activate STAT3 signaling pathway in HeLa and SiHa cells, and the expression of N‐cadherin, E‐cadherin, vimentin, MMP‐3, and MMP‐13 were examined to confirm the activation of the STAT3 signaling pathway to promote the invasion potential of cervical cancer cells." (PMID 33040485, 2020). "In sharp contrast to HNSCC, STAT3 in cervical cancer was found aberrantly expressed and constitutively activated in HPV-induced cervical carcinogenesis and the level of active STAT3 was found strongly correlated with the physical state of HPV genome in cervical precancer and cancer tissues." (PMID 33344262, 2020). "We demonstrated that RES could suppress the proliferation and metastatic potential of cervical cancer cells by inactivating phosphorylation of STAT3 at Tyr705 but not Ser727." (PMID 33040485, 2020).
cervical carcinoma (continued). "The HPV E6 oncoprotein aberrantly activates the signal transducer and activator of transcription 3 (STAT3) transcription factor and this is achieved by a virus-driven increase in the levels of the pro-inflammatory cytokine interleukin-6 (IL-6) in HPV positive cervical cancers cells." (PMID 31817106, 2019). "Our data reported herein in cervical cancer cell lines, and the evidence reported by other groups in tumor tissues, suggest that the regulatory genetic networks such as miR-21/PDCD4/AP-1 and miR-21/Let-7a/STAT3/PTEN, are highly complex and create a balance mechanism." (PMID 31427899, 2019). "Thus, IL-6 secreted from HPV positive cervical cancer cells can induce the activation of STAT3 in HPV negative cervical cancer cells via IL-6/gp130 signalling." (PMID 31226168, 2019). "Another study by the same research group demonstrated that cervical cancer cells increase IL-6 production, and the overexpression of this cytokine may promote cervical tumorigenesis by activating VEGF-mediated angiogenesis via a STAT3 pathway." (PMID 31470515, 2019). "In light of the impact of STAT3 inhibition on HPV+ cervical cancer cell proliferation, we sought to address whether the absence of active STAT3 induced apoptosis." (PMID 31226168, 2019). "Moreover, the active form of STAT3, phospho-STAT3 (p-STAT3), and two identified downstream genes of STAT3, BCL-2 and MMP-2, were consistently suppressed, which demonstrated that STAT3 is a target gene of miR-29b in cervical cancer cells." (PMID 28122338, 2017). "It is likely that STAT3-induced miR-21 contributes to a relevant part of positive feedback loop in cervical cancer cells that keeps several apoptosis-inducing regulators, including PTEN, under control, and that miR-21 inhibition relieves PTEN suppression leading to inhibition of STAT3 signaling." (PMID 26975392, 2016). "Our findings suggest that PRL could be modulating the induction of antiapoptotic genes through STAT3 activation in cervical cancer cells, without discarding the involvement of other alternate routes to those discussed in this paper." (PMID 26346346, 2015). "It is likely that STAT3-induced miR-21 contributes to an important part of positive feedback loop in cervical cancer cells that keeps various apoptosis-inducing death regulators including PTEN, under control and miR-21 inhibition alleviates PTEN suppression leading to abrogated STAT3 signaling." (PMID 25539644, 2014). "Moreover, all earlier studies did not correlate STAT3 expression in cervical lesion with the status of HPV infection, the principle agent that cause cervical cancer." (PMID 20977777, 2010). "Immunoexpression of p-Stat3 has been recognised as a predictor of poor survival in other malignancies, but, to our knowledge, the correlation between the p-Stat3 expression and prognosis in patients with cervical cancer has not been reported." (PMID 19638983, 2009). "However, the correlation between the constitutive activation of Stat3 and the prognosis of cervical cancer patients has not been reported." (PMID 19638983, 2009). "Although the constitutive activation of Stat3 has been detected in various types of human cancers, there is no report on whether Stat3 is activated in endometrial cancer and cervical cancer tissues." (PMID 17311011, 2007). "However, the constitutive activation of Stat3 in endometrial and cervical cancers has not been studied." (PMID 17311011, 2007). "Tandem mass tag proteomics and network pharmacology has shown that Hed may inhibit advanced cervical cancer cell mitochondrial autophagy by blocking the autophagy effector fraction through modulation of the target network, which is dominated by HIF-1α, Src, Akt, and Stat3." (PMID 38711526, 2024). "Additionally, the activation of the JAK/STAT3 pathway driven by IL‐6 was not identical to the previous prediction that strong STAT3 activation is representative in cervical high‐grade lesions and then withdraw in cervical cancer within tumor nests." (PMID 33694292, 2021).
cervical carcinoma (continued). "Despite synergistically enhancing the effect of paclitaxel against paclitaxel-resistant cervical cancer cells, alkaloids from Piper nigrum could also enhance mitomycin-C (MMC) therapy of human cervical cancer through suppression of Bcl-2 signaling pathway via inactivation of STAT3/NF-κB." (PMID 34395473, 2021). "Moreover, since STAT3 is required by cells to regulate various biological processes, modulation of the components of the SNHG12/miR-125b/STAT3 signaling axis may reduce the progression of cervical cancer." (PMID 31620362, 2019). "EPOR is expressed in cervical cancer, and the binding of erythropoietin (Epo) to its receptor induced cell proliferation; such cell response was related to the activation of JAK2, JAK3, STAT3, and STAT5, but not JAK1 and STAT1 in cervical cancer." (PMID 37372319, 2023). "Based on this, we examined the expression of STAT3 and MEG3 in cervical cancer tissues and found a negative correlation between them." (PMID 31320837, 2019). "Previous studies have shown that treatment of SiHa HPV16-positive cervical cancer cells with AG490, a non-specific JAK2 inhibitor, prevented STAT3 Y705 phosphorylation, however, such studies have not been performed in primary keratinocytes." (PMID 29630659, 2018). "However, whether Stat3 is activated in endometrial and cervical cancers is not known." (PMID 17311011, 2007). "Additionally, the mechanisms of LNM in cervical cancer are still not clear, and some studies have focused on changes in signalling pathways related to EMT, STAT3/p-STAT3, and immune escape." (PMID 37689639, 2023). "In a study on cervical cancer, the importance of IFN-inducible activation of STAT1 and STAT2 was demonstrated through the use of STAT1 and STAT2 knockout human HeLa cells, yet the STAT3 knockout did not have any effect on ISGs." (PMID 33329603, 2020).